RN7SL185P (RNA, 7SL, cytoplasmic 185, pseudogene)
Gene: Miscellaneous RNA gene on chromosome 15 (32,394,365 to 32,394,613, reverse strand). Ensembl gene ENSG00000275776.
Homologues: Orthologues: chimpanzee Metazoa_SRP (93% identical), pig Metazoa_SRP (57% identical). Paralogues in human: RN7SL196P (94% identical), RN7SL286P (94% identical), RN7SL539P (94% identical), RN7SL796P (94% identical), RN7SL469P (93% identical), RN7SL673P (93% identical), RN7SL628P (93% identical), RN7SL719P (93% identical), RN7SL82P (93% identical), RN7SL495P (92% identical), Metazoa_SRP (90% identical), RN7SL106P (90% identical), and 707 more.